MICG (MHC class I polypeptide-related sequence G (pseudogene))
Gene: Transcribed unprocessed pseudogene on chromosome 6 (29,812,565 to 29,812,696, reverse strand). Ensembl gene ENSG00000237042.
Diseases named in the same sentence as MICG in open-access papers:
MICG is named in the same sentence as 2 diseases in open-access papers, as found by Europe PMC text mining. Sharing a sentence is not in itself a finding about the gene and the disease. The quoted sentences say what the papers report.
infection (2 papers, 2022 to 2024). The state of being infected such as from the introduction of a foreign agent such as serum, vaccine, antigenic substance or organism. "The clone (“S”) that was the most susceptible to MicG and suffered most from virulent effects of infection in this study also expressed the strongest transgenerational virulence effect in a related study." (PMID 38651867, 2024). "We found that MicG infections result in loss of microvilli of the infected cells, which likely affects the host’s interaction with resources." (PMID 38651867, 2024). "In this study, we identified this Daphnia-infecting microsporidian previously called “MicG” and then addressed the overarching question: what is the baseline cost of MicG infection?" (PMID 38651867, 2024). "Genetic matching between host and parasite is just one of many factors determining infection success in microsporidia; factors such as developmental stage and feeding behavior of the host also seem relevant to the Daphnia—MicG interaction." (PMID 38651867, 2024). "In addition, in our laboratory infection assay, MicG infected two out of the five D. longispina clones." (PMID 38651867, 2024). "In contrast to this prediction, in a complementary study, we found that MicG infections increase host mortality after exposure to a second pathogen that invades the host through the gut, which could be a consequence of overwhelming damage done to the host’s gut." (PMID 38651867, 2024). "Therefore, prior infection with MicG might alter the ability of Daphnia to mount a hemocyte response against Metschnikowia." (PMID 36545366, 2022). "However, two of our studies on this system found strong negative effects of MicG infection." (PMID 38651867, 2024).
MICG also shares sentences with these, for which no sentence is quoted: co‐infection (1 paper).